SIRT2 (sirtuin 2)
Diseases named in the same sentence as SIRT2 in open-access papers (continued):
Sharing a sentence is not in itself a finding about the gene and the disease.
cancer (continued). "We also identified several cancer-associated SIRT2 mutants with loss of the stimulatory effects on OGG1 transcription and BER efficiency, indicating that SIRT2 functions as a tumor suppressor by promoting BER for genome stabilization." (PMID 38554113, 2024). "SIRT2 is generally considered a tumor suppressor because its expression is downregulated in most cancers, and it restricts cell cycle progression by deacetylating cell cycle-related factors and deacetylating H4K16 to allow chromatin condensation." (PMID 38554113, 2024). "SIRT2, conversely, disrupts cancer cell proliferation by inhibiting eIF5A, while SIRT3 exerts tumor-suppressive effects by regulating mitochondrial ROS and glycolysis." (PMID 39682281, 2024). "Oncogenic characteristic of SIRT2 was demonstrated in some types of cancer, while others showed the tumor suppressive role of SIRT2." (PMID 38216561, 2024). "The need for new strategies to treat cancer and the promising results of SIRT2 modulation on different types of cancers steered the continuous research of effective SIRT2 modulators." (PMID 39456864, 2024). "Increasing evidence suggests that the metabolic adaptations of T cells determine their function by reprogramming T-cell metabolism through checkpoints like IDO, IL4I1, and SIRT2, resulting in improved anti-cancer immune efficacy." (PMID 38755125, 2024). "SIRT1 helps cancer cells survive chemotherapy, SIRT2 inhibits cell growth, and SIRT3 controls mitochondrial health, while SIRT4, SIRT5, SIRT6, and SIRT7 each influence metabolism, angiogenesis, and metastasis." (PMID 39682281, 2024). "Suppression of SIRT2-mediated deacetylation reduced the invasion and tumorsphere formation of cancer cells, and K212R substitution in Ago2 prevented TM from exerting the same effect." (PMID 38649663, 2024). "Reduced SIRT2 correlates with higher-grade cancers, poorer PSA recurrence-free survival, and diminished responses to ARSIs, underscoring its potential as a therapeutic target in tumors characterized by heightened p300 activity and histone hyperacetylation." (PMID 39796040, 2024). "Building on this, our study extended the current knowledge on the ability of SIRT2 inhibition to impact cancer cell migration." (PMID 39682770, 2024). "SIRT3 and SIRT4 suppress oncogenic pathways by regulating cancer metabolism, while SIRT2 and SIRT6 influence tumor aggressiveness and androgen receptor sensitivity, with SIRT6 promoting metastatic potential." (PMID 39796040, 2024). "As a tumor suppressor, SIRT2 can restrain the expansion of cancer cells by hindering fibroblast activity and cancer angiogenesis." (PMID 37175631, 2023). "Our findings in the aggressive PCa cell line are in good accordance with previous reports that SIRT2 promotes migration and invasion in various cancers." (PMID 35278714, 2023). "Orthotopic implantation of cancer was conducted but SIRT2−/− mice only showed a mild increase in tumor growth when B16 cells were subcutaneously applied, implying a selective role of secreted SIRT2 in alleviating cancer metastasis than tumor growth in vivo." (PMID 36453571, 2023). "Treatment of a broad range of cancer cell lines with Thiomyristoyl (TM) or RK-9123016, which are potent, selective Sirt2 inhibitors that slow cell migration, sphere formation, and reduce cancer cell viability." (PMID 37628798, 2023). "On the other hand, SIRT2 can also affect the invasion and metastasis of cancer by inhibiting cancer-related macrophages, myeloid cells, and neutrophils, weakening the immune response and helping cancer cells to escape immune surveillance." (PMID 37175631, 2023). "Recently, small molecule inhibition of Sirt2 has been identified as a potential therapeutic strategy for a wide variety of cancers, including HCC." (PMID 37628798, 2023). "A study has shown that SIRT2 is highly expressed in EC and can promote cancer proliferation and metastasis by regulating the RAS/ERK pathway." (PMID 37723477, 2023).
cancer (continued). "In the same line, in recent years, a growing body of evidence has proposed a role for SIRT2 in tumorigenesis, however, its role in cancer is complicated as it has been described as both an oncogene and a tumor suppressor." (PMID 37698780, 2023). "Numerous studies have revealed that SIRT2 has a dual function in the formation of malignancies, acting as both a tumor promoter or suppressor, depending on the cancer type." (PMID 37298312, 2023). "SIRT2 inhibition can have an impact on the NF-κB/miR-21 pathway, leading to the suppression of cancer cell proliferation." (PMID 37175631, 2023). "The thiomyristoyl lysine compound (TM) was proven to be a highly potent and specific SIRT2 inhibitor in several cancer types, promoting MYC ubiquitination and degradation, among others." (PMID 37443779, 2023). "Only one gene, SIRT2, was identified as having altered methylation in cancer survivors at baseline and after training in both the cancer survivors and healthy controls." (PMID 36542473, 2023). "Intriguingly, SIRT2 promoted cancer cell metastasis presumably via deacetylating multiple extracellular proteins including ITGB3 and collagens in the microenvironment." (PMID 36453571, 2023). "Integrin extracellular domain deacetylation by SIRT2 secreted by macrophages promotes cancer cell migration." (PMID 36453571, 2023). "Next, the deacetylation effect of SIRT2 secretion from macrophages on cancer cell membrane protein was evaluated by co‐culturing THP1 cells with A549 cells in a transwell system where the two types of cells were separated by 0.4 μm pore membranes." (PMID 36453571, 2023). "On this basis, the development of SIRT2 inhibitors arresting the proliferation of cancer cells is of therapeutic relevance." (PMID 37298312, 2023). "SIRT2, a NAD(+)‐dependent deacetylase, is a member of the sirtuin family and has been implicated in various cancers." (PMID 37658623, 2023). "Intriguingly, SIRT2 promotes cancer cell metastasis presumably via deacetylating multiple extracellular proteins including ITGB3 and collagens." (PMID 36453571, 2023). "By inhibiting Wnt/β-catenin signaling, the SIRT2 promoter is activated, leading to enhanced differentiation of cancer cells and the reverse is also true." (PMID 37175631, 2023). "In contrast to the decrease in the protein expression of SIRT5, protein expression of SIRT2 was increased in aggressive cancer cells." (PMID 35278714, 2023). "BZD9L1 is a SIRT1 and SIRT2 inhibitor reported to down-regulate SIRT1 and SIRT2 gene and protein expression in healthy and cancer models in vitro and in vivo." (PMID 38002059, 2023). "As a result, SIRT2 inhibition stands out as a possible intervention strategy in the long-running fight against cancer." (PMID 36750593, 2023). "Studies have demonstrated that SIRT2 is involved in cancer metastasis and prognosis, which makes it a promising target for cancer therapy." (PMID 36770884, 2023). "Recent studies have proposed SIRT2 as a key player in aging, inflammation, cancer and neurodegenerative diseases, but its specific role in these processes seems contradictory." (PMID 37698780, 2023). "Sirtuin 2 (SIRT2) has been proposed to have a central role on aging, inflammation, cancer and neurodegenerative diseases; however, its specific function remains controversial." (PMID 37698780, 2023). "Among these three types of cancer, our results show that SIRT2 expression levels are positively correlated with prognosis in the HNSC and LUAD, and negatively in the OV cohort." (PMID 36844923, 2022). "FOXO1 is required for inducible autophagy in cancer cells, where SIRT2 deacetylates FOXO1 and forms a complex with SIRT2." (PMID 36712965, 2022). "It has been reported that ERK can bind to Sirt2, leading to increased stability and activity of Sirt2, while Sirt2 expression positively associated with ERK phosphorylation in some cancer cell lines." (PMID 35701718, 2022).
cancer (continued). "SIRT2 is essential for the protective effect of caloric restriction against high-fat diet-induced cancer." (PMID 36614171, 2022). "The present study investigated the expression levels of SIRT2 in human normal and cancer tissues, using the dominant online database TIMER2.0 and GEPIA2." (PMID 36844923, 2022). "On this basis we propose the thesis that aberrant expression of SIRT2 is an important contributor to the development of a variety of malignancies and has the prognostic potential for specific types of cancer." (PMID 36844923, 2022). "SIRT2, a NAD+-dependent class III histone deacetylase, is associated with cancer, genomic instability, and the pathogenesis of bacterial infection." (PMID 35493297, 2022). "As a tumour suppressor, SIRT2 can inhibit cancer by not only inhibiting fibroblast activity and angiogenesis but also inhibiting cancer through various metabolic pathways." (PMID 36101744, 2022). "Various types of cancer have also been examined for variation in SIRT2 expression levels between cancer and normal tissues." (PMID 36844923, 2022). "SIRT2 is also involved in cancer where it has been proposed as both a tumor suppressor and tumor promoter." (PMID 35408848, 2022). "CD8A, an important glycoprotein on the surface of T cells involved in intercellular interactions in the immune response, is highly correlated with SIRT2 expression in LUAD which are types of cancers with better prognosis." (PMID 36844923, 2022). "The benefits of SIRT2 modulation by small molecules have been demonstrated in cancer and various metabolic and neurodegenerative disorders." (PMID 35813508, 2022). "Compared with adjacent normal tissues (cancer vs. normal), we found that SIRT2 was highly expressed in CHOL, ESCA, KICH, KICP, LIHC and conversely low expressed in BRCA, KIRP, LUAD, LUSC, STAD, UCEC." (PMID 36844923, 2022). "Cambinol is an experimental inhibitor of SIRT2 and is being investigated for use in cancer treatment." (PMID 35408848, 2022). "We analyzed the relationship between SIRT2 expression levels and prognosis in different cancer populations." (PMID 36844923, 2022). "We concluded that higher mRNA and protein levels of SIRT2 affected prognosis in various types of cancers, especially in LUAD cohorts." (PMID 36844923, 2022). "In liver cancer, SIRT2 can promote mitochondrial metabolism and inhibit the E-cadherin pathway, thereby promoting cancer cell invasion." (PMID 36101744, 2022). "In brief, the current evidence suggests that SIRT2 plays dual roles in cancer, and its specific role in cancer still needs to be revealed by further studies." (PMID 36101744, 2022). "Then they showed that the miR-221-3p–SIRT2 axis decreases the antisenescent effects of exosomeMIF in cardiomyocytes treated with DOX chemotherapy for cancer." (PMID 34943825, 2021). "A new class of SIRT2 inhibitors, S-trityl-L-cysteine, was identified to have potential therapeutic effects on cancer." (PMID 34943825, 2021). "SIRT2 has been extensively studied due to its diverse physiological roles and its potential as a therapeutic target for certain cancers and neurological disorders." (PMID 34368168, 2021). "Regardless, inhibition of SIRT2 leads to degradation of c-Myc and reduced growth in a broad variety of cancer cells, demonstrating its efficacy as a drug target." (PMID 34368168, 2021). "As a result, while the functions of SIRT2 in tumorigenesis have been reported and reviewed in many studies, the connection and mechanism between SIRT2 and the cancer are less established." (PMID 33705642, 2021). "Sirtuin2 (SIRT2), a member of the sirtuin protein family, plays a critical role in growth and metastasis in various cancers." (PMID 35177983, 2021). "Recent experiments have focused on revealing role of sirtuin-2 (SIRT2) in cancer and providing rationale for its therapeutic targeting." (PMID 33921908, 2021). "The mechanism-based SIRT2 inhibitors also demonstrated strong anti-cancer effects in cellular and animal models." (PMID 34650436, 2021).
cancer (continued). "Among all members of the sirtuin family, SIRT1 and SIRT2 have been extensively studied due to their prominent role in cancer cell fate." (PMID 34445277, 2021). "Earlier works have found that the unusual quantity of SIRT1 and SIRT2 were related to a wide range of malignant tumors." (PMID 33705642, 2021). "SIRT2 was found to be a critical regulator of a variety of cancer processes including tumor growth, invasion and metastasis." (PMID 35177983, 2021). "SIRT6 role in cancer is reminiscent of other sirtuins such as SIRT2, which has been shown to act as either tumor suppressor or promoter in breast cancer, depending on tumor grade." (PMID 33800266, 2021). "The NAD-dependent histone deacetylase known as SIRT2 shows promise as a therapeutic target in cancer treatment." (PMID 34155309, 2021). "As a result, cancer cells that possessed lower levels of Sirt2 protein were more sensitive to the cytotoxic effects of the respective drugs and vice versa." (PMID 35008351, 2021). "With more reports highlighting SIRT2 as a tumor activator, numerous SIRT2 inhibitors have been developed and evaluated in cancer models." (PMID 34650436, 2021). "On the other hand, the role of tubulin deacetylase SIRT2 in cancer is controversial, as SIRT2 exerts either tumor-suppressive or oncogenic properties." (PMID 35008169, 2021). "Several studies have been reported for the human isotype Sirt2 in the modulation of cancer pathogenesis, inflammation, metabolic diseases, and neurodegeneration, projected the regulation of Sirt2 activity as a promising approach for pharmaceutical intrusions." (PMID 33986372, 2021). "SIRT2 can suppress migration and invasion of cancer cells via isocitrate dehydrogenase 1 (IDH1) deacetylation." (PMID 33921908, 2021). "In Kim’s study, among 36 cancer tissues tested, 66.7% of the tissues maintained low or intermediate levels of SIRT2 expression." (PMID 33014852, 2020). "Based on the existing research, this review summarizes the physiological functions of SIRT2 and its mechanisms in cancer." (PMID 33014852, 2020). "HRD1 knockdown via shRNA appeared to inhibit the proliferation of A549 and H446 cancer cells, while SIRT2 overexpression or knockdown led to the reverse result." (PMID 31932479, 2020). "Recently, growing interest has been focused on the therapeutic potency of SIRT2 inhibitors not only in cancer therapy, but also in several neurodegenerative diseases, including PD." (PMID 32033023, 2020). "Revealing the regulatory mechanism of SIRT2 in suppressing tumor formation would be of great significance in cancer therapy." (PMID 31932479, 2020). "In concordance with these results, Sirt2 inhibition with small molecules such as Sirtinol, Cambinol, AC-93253, etc., has shown to be useful in treating many cancer cell lines including prostate, pancreas, breast, oral, and lung cancer cell lines." (PMID 32698385, 2020). "Recent consensus seems to reconcile these contradictory findings by taking into account disease-specific contexts such as cancer sub-type, expression pattern of SIRT2 and its substrate proteins as well as their roles in oncogenic signaling." (PMID 31973227, 2020). "Our present study extends the understanding of the role of SIRT2 in cancer by identifying its downregulating effect on the metastasis potential of NSCLC cells with high expression level of AKR1C1." (PMID 32104503, 2020). "Because SIRT2 is expressed in a wide range of tissues and organs and exerts variable physiological functions, its role in cancers is complicated." (PMID 33014852, 2020). "In this study, we aimed to identify the role of SIRT2 in oxidative stress and cisplatin response in cancer." (PMID 33207824, 2020). "The purpose of this review is to summarize the physiological functions of SIRT2 and its mechanisms in cancer." (PMID 33014852, 2020). "The dysregulation of SIRT2 has been found to play a role in cancer progression and has also been suggested as a tumor suppressor." (PMID 31932479, 2020).
cancer (continued). "We found different expression patterns of SIRT2 in cisplatin-sensitive (A2780/S) and cisplatin-resistant (A2780/CP) cancer cells with cisplatin treatment, where SIRT2 expression was augmented only in A2780/S cells." (PMID 33207824, 2020). "At the same time, some studies have shown that SIRT2 expression was relatively higher in cancer tissues and that this was positively related to increased microscopic vascular invasion and poor prognosis as an oncogene." (PMID 33207824, 2020). "The PROteasome TArgeting Chimera (PROTAC), a recently introduced technology, can overcome some of the limitations, since it degrades proteins in a spatiotemporal manner, as we have hijacked SIRT2 as a potential anti-cancer drug target." (PMID 32033023, 2020). "Our previous reports and studies by other groups have shown that pharmacological inhibition or genetic downregulation of SIRT2 has an anti-cancer effect in various malignancies which corroborates our observation in the present study." (PMID 31973227, 2020). "A thio-myristoylated dipeptide inhibitor of SIRT2 with nanomolar potency was found to promote degradation of c-myc and have anti-cancer activity in multiple cell lines." (PMID 31973227, 2020). "The results of this study identify the miR‐212‐5p/SIRT2 axis as a new factor governing malignant cancer cell behaviours and clinical outcomes." (PMID 32697380, 2020). "As with SIRT2, there are conflicting reports of cancer suppressor and oncogenic activities of SIRT1 and 3 in various tumor types." (PMID 31973227, 2020). "A recent study indicated that TM is tenfold more potent than TB in inhibiting SIRT2 in vitro, and displayed anti-proliferation activity toward various human cancer cells and mouse xenograft models of human breast cancer." (PMID 32170178, 2020). "Altering the localisation of SIRT2 has considerable effects on its biological activity as reports have shown that mislocalisation of SIRT2 can promote tumorigenesis and cancer progression." (PMID 32042025, 2020). "We next explored the possible mechanisms by which SIRT2 regulates the immune status in cancer by altering CD8+ T cells differentiation." (PMID 33061819, 2020). "The role of SIRT2 in cancer is thus complex with multiple competing mechanisms, and therefore, SIRT2 cannot be simply considered as an oncogene or a tumor suppressor." (PMID 33014852, 2020). "Recent emerging evidence has suggested the potential regulatory role of SIRT2 in carcinogenesis, as Sirt2-/- mice develop cancers in multiple organ systems." (PMID 33061819, 2020). "The discrepancy between the two studies is likely due to the overlapping and compensatory roles played by SIRT1 and SIRT2 in cancer, whilst inhibition of one leads to the induction of the other." (PMID 32372224, 2020). "Newly synthesized cambinol analogs having high specificity for SIRT2 were found to be toxic to in a panel of cancer cell lines." (PMID 31973227, 2020). "Similar to Sirt1, the data related to the role of Sirt2 in cell proliferation and development of cancer are controversial." (PMID 32698385, 2020). "In contrast, splitomicin analogs have shown activity against SIRT1 and SIRT2 as well as antiproliferative properties in cancer cells." (PMID 30761005, 2019). "SIRT2 is upregulated in cancer tissues relative to adjacent normal tissues in several kinds of cancer." (PMID 31817470, 2019). "Although controversial roles for SIRT2 in cancer have been described, our data show that SIRT2 exhibits tumor suppressive properties upon calorie restriction." (PMID 31970087, 2019). "SIRT2 inhibitors showed antiproliferative effects against different cancer cell lines such as luminal and triple-negative breast cancers, leukemia of different genotypes, and cervical cancer." (PMID 31510043, 2019).